SSTR2 (somatostatin receptor 2)
Diseases named in the same sentence as SSTR2 in open-access papers (continued):
Sharing a sentence is not in itself a finding about the gene and the disease.
pituitary adenomas (22 papers, 2013 to 2025). "Another AIP variant, a T171I missense mutation, was found in three patients with pituitary adenoma and was associated with decreased expression of Sstr2 (somatostatin receptor 2), which is needed for responsiveness to somatostatin analogs." (PMID 38479600, 2024). "In this study, we present a large evaluation of somatostatin receptor 2 (SSTR2) expression in pituitary adenomas (PA), identifying thyrotroph and somatotroph lineages as those with the most frequent and intense expression." (PMID 40770587, 2025). "SSTR2 rs2236750 and SSTR5 rs34037914 genes’ single-nucleotide polymorphisms were analyzed to evaluate the associations with pituitary adenoma size." (PMID 39202532, 2024). "Previous reports of SSTR mRNA expression in GH-secreting pituitary adenomas in humans describe SSTR5 > SSTR2 whereas SSTR1 and SSTR3 expression can be highly variable and SSTR4 expression is absent." (PMID 30620005, 2019). "In 1994, Greenman and Melmed analyzed SSTR 3, SSTR4, and SSTR5 in 33 pituitary adenomas and SSTR1 and SSTR2 in 27 pituitary adenomas using RT-PCR, including 2 and 3 ACTH-producing adenomas, respectively." (PMID 30627156, 2018). "Therefore, this study aims to investigate the Ki-67 labeling index, SSTR2 rs2236750, SSTR5 rs34037914, and AIP rs267606574 polymorphisms, serum SSTR2, SSTR5, and AIP levels, and their association with the development of pituitary adenomas." (PMID 39202532, 2024). "Further investigations found that heterogeneous signals in MRS analysis could possibly deliver information about the subtype of pituitary adenoma and that the choline to creatine ratio may predict the rate of expression of SSTR2 and therefore give information about the effect of medical therapy." (PMID 34209497, 2021). "SSAs such as Octreotide and Lanreotide, which bind to somatostatin receptor 2 (SSTR2), and to a lesser extent, to SSTR5 and SSTR3, are effective in the treatment of secreting pituitary adenomas, but are poorly efficacious in NFPAs." (PMID 37444563, 2023). "SSTR2 and SSTR5 as primary SSTRs expressed in growth hormone secreting pituitary adenomas, are primary targets in somatostatin analogue therapy." (PMID 35053382, 2022). "Somatoprim, another second-generation SSA, is a multi-receptor targeting analog with a preference for SSTR2, SSTR4, and SSTR5, which was trialed in vitro on growth hormone (GH)-secreting pituitary adenomas." (PMID 33854479, 2021). "It is used in the treatment of pituitary adenoma, where SSTR5 is more highly expressed than SSTR2." (PMID 39011594, 2024). "Nonfunctioning pituitary adenomas (NFPAs) express both D2R and SSTR2 and, consequently, may respond to TBR-760." (PMID 32591776, 2020). "Of the 5 SSTRs identified, SSTR2 and SSTR3 are expressed in most nonfunctioning pituitary adenoma samples, whereas SSTR5 is only expressed in a minority of tumors." (PMID 40255441, 2025). "In pituitary adenomas, which secrete GH, this receptor was found to be prominently expressed, along with SSTR5 and SSTR2; interestingly, in the case of pituitary adenomas secreting ACTH, SSTR2 expression was not usually detected." (PMID 39329930, 2024). "While SSTR3 is expressed in most pituitary adenomas, independent of the functional type, SSTR5 and SSTR2 (SSTR5 more than SSTR2) are widely expressed in somatotroph, thyrotroph, corticotroph, lactotroph, and gonadotroph adenomas and are probably involved in the regulation of hormonal secretion." (PMID 32121432, 2020).
pancreatic cancer (21 papers, 1999 to 2025). "Among the five SSTRs, the SSTR subtype 2 was found to be expressed at relatively high levels in pancreatic tumor cells and tumor blood vessels and the loss of SSTR2 promoted the development of human PDAC (see 5.2)." (PMID 40134804, 2025). "In contrast to normal tissue or benign lesions, there is a loss of SSTR2 gene expression in pancreatic carcinoma and advanced colorectal cancer and their respective metastases." (PMID 24137418, 2013). "Hence, loss of Sstr2 from murine pancreatic tissues resulted in the following sequence of signaling activation that culminated in increased expression of Cxcl16 and pancreatic tumor formation: Pi3k/Akt, NF-κB, oncogenic Kras." (PMID 40134804, 2025). "SSTR2 is an inhibitory G protein-coupled receptor, the expression of which is lost in most human pancreatic cancers." (PMID 39682758, 2024). "Most studies concluded that the level of SSTR2 expression in the tissues affected by pancreatic cancer is considerably higher than that of the adjacent healthy tissues." (PMID 38791582, 2024). "The results of quantitative reverse transcription polymerase chain reaction (QRT-PCR) assays demonstrated that SSTR2 mRNA is expressed in all three types of investigated pancreatic cancer cell lines, with varying degrees of abundance." (PMID 38791582, 2024). "Tissue specimens of pancreatic cancer displayed decreased mRNA expression for SSTR2 and SSTR5 when compared with the normal tissue adjacent to the carcinoma." (PMID 38203605, 2023). "Most human pancreatic cancers lack SSTR2 expression and exhibit apoptosis once transfected with SSTR2." (PMID 38203605, 2023). "On pancreatic cancer cells, it showed that octreotide, one of the popular somatostatin analogues, activates intrinsic apoptosis pathways via SSTR2 and SSTR3." (PMID 38201544, 2023). "Several studies have demonstrated the decrease in cell proliferation induced by SST and SST analogs in SSTR2-positive pancreatic cancer cells." (PMID 29700299, 2018). "Radiosensitization by PARPi during the 177Lu-octreotate-based PRRT of osteosarcoma cell line U2OS expressing exogenous SSTR2 and of rat pancreatic tumor cell line Ca20948 expressing endogenous SSTR2 has been recently reported." (PMID 29872498, 2018). "We propose that SSTR-2 plays an important role in clinical implications for patients with pancreatic cancer undergoing somatostatin or its analog therapy." (PMID 25890201, 2015). "The expression rates of SSTR-2 mRNA in cancer and adjacent tissue of 108 patients with pancreatic cancer were 81.5% (88/108) and 97.2% (105/108), respectively; SSTR-3 mRNA expression rates were 69.4% (75/108) and 55.6% (60/108)." (PMID 25890201, 2015). "Because the current study shows that the ability of somatostatin to inhibit tumor cell growth is mediated by SSTR-2, it is very important for patients suffering from pancreatic cancer to receive somatostatin treatment." (PMID 25890201, 2015). "From the results of this study, there were 88 cases with positive expression of SSTR-2 mRNA out of 108 pancreatic cancer cases; thus, the rate was 81.5%." (PMID 25890201, 2015). "Re-introduction of SSTR2 in pancreas cancer by gene transfer robustly inhibited tumor cell proliferation and tumorigenicity." (PMID 25010045, 2014). "SSTR2 expression was selectively lost in 90% of the human pancreatic carcinomas and derived pancreatic cell lines." (PMID 24137418, 2013). "Therefore, the novel 5-pentynecarbonyl-octreotide-conjugated liposomal paclitaxel presents a promising delivery system specific to pancreatic cancer cells and tissues with high expression of SSTR2." (PMID 38791582, 2024).
pancreatic cancer (continued). "The results suggest that SSTR2 gene transfer may represent a novel gene therapy strategy for the treatment of pancreatic cancer." (PMID 38201544, 2023). "SSTR2 itself is considered to be a tumor suppressor demonstrating significant reduction in pancreatic tumor growth after adenoviral vector-based SSTR2 gene transfer in experimental pancreatic cancer." (PMID 28467778, 2017). "We propose that the SSTR-2 could play an important role in clinical implications for patients with pancreatic cancer undergoing somatostatin or its analog therapy." (PMID 25890201, 2015). "In addition, gene transfer of SSTR2 inhibited metastatic progression in two different pancreatic carcinoma models." (PMID 25010045, 2014). "In vitro and in vivo studies suggest that SSTR1, SSTR2, and SSTR5 suppress the growth of pancreatic cancer." (PMID 37900156, 2023). "mRNA expression of SSTR2 and SSTR5 has been shown in different pancreatic cancer cell lines including Panic-1, MIA PaCa-2 and Hs 766T." (PMID 38203605, 2023). "In this study, we detected the expression of somatostatin receptor subtypes SSTR-2, SSTR-3, and SSTR-5 messenger RNA (mRNA) from 108 cases of cancer tissue and adjacent tissue in patients with pancreatic cancer using RT-PCR method." (PMID 25890201, 2015). "Our study is aimed at exploring the cause from different therapeutic effects of somatostatin and its analogs on human pancreatic cancer and their relationship between changes of SSTR-2 gene expression and expression of SSTR-2, SSTR-3, and SSTR-5 genes." (PMID 25890201, 2015). "The expression of somatostatin receptor subtypes SSTR-2, SSTR-3, and SSTR-5 messenger RNA (mRNA) in 108 cases of cancer tissue and adjacent tissue in patients with pancreatic cancer was detected by reverse transcriptase polymerase chain reaction (RT-PCR)." (PMID 25890201, 2015). "The contributing genes to this pathway, e.g. CCKBR, CHRM5, EDNRA, LPAR1, SSTR2/3, and SCTR, have diverse functions in regulating the endocrine and exocrine functions of the pancreas, which are highly relevant to pancreatic cancer." (PMID 23056513, 2012). "Stable expression of SSTR2 in human PDAC cells, or Sstr2 in hamster PC-1 and PC-1.0 pancreatic cancer cells, led to constitutive activation of SSTR2/Sstr2 and activation of a stable autocrine negative loop that restored the growth inhibitory effect and decreased tumorigenicity." (PMID 40134804, 2025). "The system consisted of liposomes as carriers, an anticancer drug (paclitaxel) as a chemotherapeutic agent, and a modified synthetic somatostatin analog, 5-pentacarbonyl-octreotide, a ligand for somatostatin receptor 2 (SSTR2), as a targeting moiety for pancreatic cancer." (PMID 38791582, 2024). "In experimental pancreatic tumor, the growth of both functioning pancreatic tumors and nonfunctioning tumors with SSTR-2 gene expression is inhibited by somatostatin, while there is no inhibitory effect on non-SSTR-2 gene expression cells." (PMID 25890201, 2015). "Therefore, in relation to drug receptor binding affinity and organ-specific aspects, we studied SSTR-2, SSTR-3, and SSTR-5 expression in the pancreatic cancer." (PMID 25890201, 2015). "In pancreatic cancer the Src homology region 2 domain-containing tyrosine phosphatase 1 (SHP-1) is able to de-phosphorylate the epithelial cell adhesion molecule E-cadherin, thereby stabilizing inter-epithelial cell junctions in a SSTR2-dependent fashion." (PMID 25010045, 2014). "Reintroducing SSTR2 in human pancreatic cancer cells by stable expression resulted in a constitutive activation of SSTR2 and an inhibition of cell growth in the absence of an exogenous ligand." (PMID 24137418, 2013). "In vitro data also demonstrated absence of SSTR2 expression, suggesting pancreatic cancer not to be a potential target for treatment with SST analogues." (PMID 10027326, 1999).
glioma (20 papers, 2014 to 2025). A benign or malignant brain and spinal cord tumor that arises from glial cells (astrocytes, oligodendrocytes, ependymal cells). "Similar correlation has been found in gliomas, where high SSTR2 levels are linked to lower WHO grades and better prognoses." (PMID 41002582, 2025). "Extensive expression of SSTR2 has been previously reported in both low and high grades of glioma, which makes it a susceptible target for peptide based drug delivery." (PMID 29029435, 2017). "SSTR2 is overexpressed in several human cancers, including neuroendocrine tumors (NETs), small-cell lung carcinomas (SCLCs), and certain gliomas." (PMID 41002582, 2025). "MM also typically expresses EMA and SSTR2, which helps differentiate it from gliomas and germ cell tumors, both of which are usually EMA-negative." (PMID 40842573, 2025). "Somatostatin receptor type 2 (SSTR2) is highly prevalent in glioma cells and the endothelial cells of proliferating vessels within gliomas." (PMID 39861688, 2024). "SSTR2 inhibits the cAMP levels in glioma cells and, in addition to the modulation of potassium channels leading to the hyperpolarization in glioma cells of human origin." (PMID 38203605, 2023). "Contrasting results have been demonstrated in previous studies, in which SSTR2 overexpression in glioblastomas and low SSTR2 expression levels in WHO-grade-II–III gliomas were detected." (PMID 34577572, 2021). "The potential role of PRRT in patients with gliomas that express SSTRs (and particularly SSTR2) has been demonstrated." (PMID 34577572, 2021). "There is a piece of evidence that somatostatin receptors (SSTRs), mainly subtype 2 (SSTR2), are significantly expressed in both glioma and glioma vasculature endothelial cells." (PMID 31936832, 2020). "Similar results were obtained regarding SSTR2 mRNA expression in the TCGA low grade glioma, subtype IDH-mutant and 1p/19q-codeleted, dataset." (PMID 30193580, 2018). "When categorized into two groups according to the median score, we observed a better overall survival in glioma with high SSTR2 mRNA expression (p = 0.056) among the low grade glioma IDH-mutant and 1p/19q-codeleted subgroup." (PMID 30193580, 2018). "Among the independent TCGA low-grade glioma dataset we observed a higher SSTR2 mRNA expression in IDH-mutant glioma when compared to IDH-wild type (p < 0.001)." (PMID 30193580, 2018). "SSTR2pep-DIM-NPs was found to not only cross the in vitro BBB system, but also delivered the drug-load specifically to the SSTR2 overexpressed glioma tissue of the tumor bearing rats." (PMID 29029435, 2017). "Our analysis included a total of 184 gliomas and is to our knowledge the most extensive effort to characterize SSTR2 expression in different glioma subtypes assessed by the new 2016 WHO classification system." (PMID 28467778, 2017). "We have recently demonstrated that PET/CT imaging with intravenously injected 68Ga-DOTA-peptide targeting SSTR2 provides limited value in defining suitable patients with high-grade glioma for targeted radionuclide therapy." (PMID 28467778, 2017). "In the present study, expression of SSTR2 was found to be very high in human and rat glioma samples." (PMID 29029435, 2017). "These nanoparticles were tagged with a novel peptide against somatostatin receptor 2 (SSTR2), a potential target in glioma." (PMID 29029435, 2017). "In C6 glioma cells, proliferation was inhibited by activation of SSTR2 as measured by [3H]thymidine incorporation assays." (PMID 25010045, 2014). "Interestingly, in their cohort, SSTR2 was significantly overexpressed (p = 0.0001) in the 1p/19q-codeleted group when compared to the EGFR amplified high grade gliomas." (PMID 30193580, 2018). "Furthermore, similar results were obtained regarding SSTR2 mRNA expression in an independent cohort using the low grade gliomas TCGA dataset." (PMID 30193580, 2018). "Furthermore, IDH-mutant and 1p/19q-codeleted gliomas presented with the highest level of SSTR2 mRNA expression (p < 0.001)." (PMID 30193580, 2018).
glioma (continued). "Autoradiography and Northern blot analyses are unable to define the exact location of the receptor making it impossible to differentiate SSTR2 expression in tumor cells from other cell types such as macrophages which are abundant in gliomas and known to express SSTR2." (PMID 28467778, 2017). "SSTR2 status was an independent prognostic marker for PFS after adjustment to glioma grade." (PMID 25977882, 2015). "Comparable observations have also been reported for SSTR2 in non-mutated human gliomas." (PMID 38203605, 2023). "Since the previous studies have explored the role of the signature genes METTL7B, SSTR2, OXTR, CDKN2C, and H19 in glioma, while TNFRSF11B has been poorly studied, we examined the functional impact of TNFRSF11B on LGG cell behavior." (PMID 37713112, 2024). "The expression of SSTR has been reported in approximately 25% of gliomas with variable expression between LGG and HGG but with decreasing expression of SSTR2 in the most aggressive gliomas." (PMID 39472354, 2024). "Amongst all five SSTR subtypes, SSTR2 is the receptor subtype that was found to be overexpressed in different WHO-grade solid human gliomas, as well as in human glioma cell lines." (PMID 38203605, 2023). "Studies with limited number of patients have reported high SSTR2 expression in glioblastomas and low expression in grade II–III gliomas, while others have detected the opposite." (PMID 28467778, 2017). "In the present study, results from the IHC and IB analysis suggested that upon sustained release from the nanoformulation, DIM inhibited EGFR pathway activation in both SSTR2 and EGFR overexpressed rat glioma samples." (PMID 29029435, 2017). "Confocal laser scanning microscopy (CLSM) and TEM were therefore used to study internalization and intracellular trafficking of both SSTR2 peptide tagged and untagged PLGA nanoparticles in C6 glioma cells." (PMID 29029435, 2017). "In this study, expressions of SSTR2 and EGFR were investigated in both human and rat glial tumor samples (n= 25 each) and all were found immunopositive." (PMID 29029435, 2017). "SSTR2 could mediate the cytostatic effects of somatostatin by activating phosphotyrosine phosphatase PTPeta and inhibiting ERK1/2 activity in C6 glioma cells." (PMID 34961815, 2021). "Other than SSTR2, EGFR was also highly expressed in glioma samples." (PMID 29029435, 2017).